WNT1 (Wnt family member 1)
Diseases named in the same sentence as WNT1 in open-access papers (continued):
Sharing a sentence is not in itself a finding about the gene and the disease.
developmental delay (3 papers, 2017 to 2023). "The palate of both Ttc21bf/aln;Wnt1-Cre and Ttc21bf/aln;Crect were cleft, however Ttc21bf/aln;Wnt1-Cre palatal shelves appeared to be elevated and patent due to either developmental delay or palatal insufficiency, whereas the palatal shelves in the Ttc21bf/aln;Crect were hypoplastic and dysmorphic." (PMID 28346501, 2017). "In addition, all patients with developmental delays or neurological deficits exhibited bilateral ptosis, a unique finding that may contribute to the diagnosis of WNT1-OI." (PMID 37559063, 2023). "About half of the patients with WNT1-related OI have neurological or brain abnormalities, including dilated ventricles with atrophic changes, cerebellar hypoplasia with short midbrain or type I Chiari malformation, and about 40% have severe intellectual disability or developmental delay." (PMID 37559063, 2023).
diabetic nephropathy (3 papers, 2017 to 2025). "Previous study found that diabetic nephropathy mice has the down-regulated Klotho and up-regulated Wnt1 and β-catenin in protein and mRNA level, exasperate damage containing proteinuria, lipid disorders, and pathological hurt of kidney tissue." (PMID 39230198, 2024).
ductal adenocarcinomas (3 papers, 2012 to 2013). "Using 100 cases of invasive ductal carcinoma tissue, we screened expressions of RSPO1, WNT1, WT1, P16, and SDC1 using immunohistochemistry." (PMID 24373193, 2013). "To better understand the mechanisms of the SDC1 expression in invasive ductal carcinoma, we studied the correlations between SDC1 expression and related gene expressions (RSPO1, WNT1, WT1, and P16)." (PMID 24373193, 2013).
glioblastoma (3 papers, 2016 to 2023). The most malignant astrocytic tumor (WHO grade IV). "Similarly, both Wnt1 and Wnt3a support stem-like cells in glioblastoma multiforme (GBM)." (PMID 27355964, 2016).
liver fibrosis (3 papers, 2015 to 2020). "To seek an explanation for the effect of Wnt1 or Wnt5a on liver fibrosis, we knockdown Wnt1 and Wnt5a in HSC-T6 cells by siRNA transfection." (PMID 26537990, 2015). "Our study found that the expression of Wnt genes (Wnt1, Wnt2, Wnt3, Wnt3a and Wnt5a) was upregulated, and Wnt pathway signalling in hepatocytes was active during the progression of schistosomiasis-induced liver fibrosis." (PMID 28331224, 2017). "Thus, upregulated Wnt1 and Wnt5a in MCD diet-induced steatofibrosis mice may account for the steatohepatitis-related liver fibrosis in the present study." (PMID 32461992, 2020).
Myocardial fibrosis (3 papers, 2013 to 2025). "Prior studies have shown that miR-152-3p inhibits CFs proliferation and migration by suppressing the Wnt1/β-catenin pathway, resulting in a reduction in myocardial fibrosis." (PMID 40822849, 2025). "A recent study also showed that Wnt ligand (Wnt-1/Wnt-5a) secretion was a necessary downstream step for TGF-β–mediated myofibroblast differentiation and myocardial fibrosis in experimental autoimmune myocarditis." (PMID 33442383, 2020).
neuroblastoma (3 papers, 2015 to 2021). Neuroblastoma (NB) is the most common solid, extracranial childhood tumor. "Our findings in this study exhibit that linagliptin ameliorates Aβ-induced cytotoxicity in human neuroblastoma cells, and a part of this protective effect is mediated through the activation of Wnt1 signaling and control of cellular inflammation." (PMID 34425652, 2021). "In this study, exposure of neuroblastoma cells to Aβ1-42 significantly decreased Wnt1 level, which is consistent with an investigation." (PMID 34425652, 2021). "Moreover, Aβ1-42 treatment impaired pCREB, PKCε, and Wnt1 signaling in human SH-SY5Y neuroblastoma cells." (PMID 34425652, 2021). "Moreover, genes that have previously been established to drive neuroblastoma progression and migration, including DBH, NOTCH1, RET and WNT1, were down regulated in response to TRPM7 knockdown." (PMID 25797249, 2015).
ptosis (3 papers, 2020 to 2024). The drooping of the upper eyelid. "Genotypic and phenotypic analysis unraveled ptosis as a unique phenotype in patients with WNT1 variants." (PMID 33093841, 2020). "In patients with WNT1 mutations, those with ptosis also showed more severe skeletal dysfunctions including higher fracture frequency and unable to walk independently (80%), as compared to those without ptosis." (PMID 33093841, 2020). "We noticed that AR-OI patients carrying WNT1 mutations were prone to developing ptosis, with 46.67% penetrance." (PMID 33093841, 2020). "The most distinct phenotypic characteristic in Chinese AR-OI patients was a unique ptosis phenotype, which was presented almost exclusively in patients associated with WNT1 variants." (PMID 33093841, 2020). "The mechanism of the development of ptosis in patients with WNT1 variant-induced AR-OI remains to be elucidated in future studies." (PMID 33093841, 2020). "Interestingly, ptosis represents a unique phenotype of patients carrying WNT1 variants, and it was rare in patients harboring other pathogenic genes." (PMID 33093841, 2020). "Although Wnt1 is crucial for brain development, only 6 patients in our cohort (6/25) showed ptosis that is related to neuronal defects." (PMID 39126373, 2024). "Statistical analysis was conducted for WNT1, SERPINF1 and FKBP10, with > 3 probands, and only ptosis was significantly different between groups." (PMID 33093841, 2020).
acute kidney injury (2 papers, 2021). Sudden and sustained deterioration of the kidney function characterized by decreased glomerular filtration rate, increased serum creatinine or oliguria. "It has been demonstrated that exogenous Wnt1 prevents acute kidney injury and subsequent chronic renal injury." (PMID 35059392, 2021).
adenosquamous carcinoma (2 papers, 2004 to 2014). A carcinoma composed of malignant glandular cells and malignant squamous cells. "Analysis of 6 of these adenosquamous carcinomas revealed the presence of β-catenin in the nucleus and increased expression of either WNT1, WNT6, WNT8B and WNT10A or combination thereof." (PMID 25217618, 2014). "Myoepithelial differentiation is 'constitutive' to specific tumor types, for example adenosquamous carcinomas, adenomyoepitheliomas, and adenocarcinomas associated with the active mouse mammary tumor virus (MMTV) and the wingless-related MMTV integration site 1 (Wnt1) transgene." (PMID 15535849, 2004).
Arthritis (2 papers, 2020 to 2023). Inflammation of a joint. "In general, berberine, palmatine, coptisine, jatrorrhizine, magnoflorine and jatrorrhizine hydrochloride in CC play the role in treating arthritis by regulating Wnt1/β-catenin and PI3K/AKT/mTOR signaling pathways." (PMID 37637408, 2023). "At the molecular level, CC plays a critical role in the treatment of arthritis by regulating NF-κB, Wnt1/β-catenin and PI3K/AKT/mTOR signaling pathway, inhibiting the expression of IL-6, IL-1β, MMP-3 and TNF-α." (PMID 37637408, 2023). "At the molecular level, six components including berberine can improve RA, OA, GA and other types of arthritis by regulating PI3K/AKT, Wnt1/β-catenin and NF-кB signaling pathways." (PMID 37637408, 2023). "The results from in vivo experiments indicated that EZP combined with MTX reduced arthritis severity, alleviated ankle bone damage, increased BALP and decreased TRACP serum levels, and regulated the mRNA expression of Wnt1, LRP5, β-catenin, Runx2, BALP, and BGP in the ankles." (PMID 32218732, 2020).
Ataxia (2 papers, 2013 to 2024). Ataxia refers to impaired coordination of voluntary muscle movement. "Deletion of Runx3 in neurons (Wnt1-Cre/Runx3f/f;) recapitulated the ataxia phenotype that occurred in Runx3-deficient mice, and was associated with severe skeletal scoliosis." (PMID 39715266, 2024). "We found that lidocaine injection into IO decreased opisthotonus of Wnt1-Cre;Itpr1flox/flox mice, although tremor of limbs and ataxia were still observed." (PMID 24109434, 2013).
atherosclerosis (2 papers, 2017 to 2023). A disease characterized by the build-up of fatty material and calcium deposition in the arterial wall resulting in partial or complete occlusion of the arterial lumen. "In addition, Sirt6 interacts with SNF2H as a novel regulator during atherosclerosis, inhibits Wnt1/β-catenin signalling and promotes lipid degradation." (PMID 37736721, 2023).
autoimmune myocarditis (2 papers, 2017 to 2020). Autoimmune myocarditis is an autoimmune disease that affects the heart. "During cardiac fibrosis resulting from autoimmune myocarditis, Wnt1 and Wnt5a expression is induced in regions of immune cell infiltration, and inhibition of Wnt signaling via administration of soluble pathway inhibitors prevents cardiac fibrosis and improves cardiac function." (PMID 28959037, 2017).
brain injuries (2 papers, 2022 to 2025). "Behavioral indicators in the HRW group were also markedly better than in the IR group, suggesting that HRW may improve radiation-induced brain injury and cognitive deficits via the Wnt1 pathway." (PMID 40867844, 2025). "Additionally, overexpression of WNT1 suppressed the inflammatory response and promoted M2 polarization, alleviating inflammation-sensitized neonatal brain injuries." (PMID 35603707, 2022). "Wnt1 activated LKB1 to suppress inflammation-mediated activation of microglia, promote M2-type microglia conversion via the AMPK pathway, and alleviate inflammation-sensitized neonatal brain injuries." (PMID 35603707, 2022).
chronic kidney disease (2 papers, 2021 to 2022). Impairment of the renal function secondary to chronic kidney damage persisting for three or more months. "Clinically, a randomized controlled trial showed that treatment with Qingshen granules could lower the levels of serum Wnt1, β-catenin, α-SMA, and E-cadherin in patients with chronic renal failure." (PMID 36059935, 2022).
colon adenocarcinoma (2 papers, 2019 to 2020). "For colon adenocarcinoma, the lack of association between intratumoral T cytotoxic cells and Wnt1 gene expression seems to be confirmed by IHC-based CD8+ T cell enumeration (Dr Tan Bee Huat Iain, personal communication)." (PMID 30926812, 2019). "The expression of WNT1, APC was decreased in colon adenocarcinoma, and that of CTNNB1 was decreased in cholangiocarcinoma." (PMID 32764696, 2020).
congenital hydrocephalus (2 papers, 2016 to 2024). Hydrocephalus that is present at birth. "Only conditional mutants generated using Pax7−Cre or Wnt1-Cre developed early onset congenital hydrocephalus due to stenosis of the third ventricle, suggesting that loss of neuroepithelial Pax3 is sufficient to disturb third ventricle morphogenesis." (PMID 26949601, 2016).
cortical dysplasia (2 papers, 2012 to 2024). "Previous studies showed that EMX2 expression was found to negatively regulate the Wnt pathway and loss of Emx2 function leads to ectopic expression of Wnt1 in the developing telencephalon and cortical dysplasia." (PMID 39628661, 2024). "EMX2 is found as a direct repressor of Wnt1 expression, and knocking-down of EMX2 gene induces ectopic expression of Wnt1 in the developing telencephalon and cortical dysplasia." (PMID 23029345, 2012).
Encephalocele (2 papers, 2021 to 2024). A neural tube defect characterized by sac-like protrusions of the brain and the membranes that cover it through openings in the skull. "All double heterozygotes, C1-C4flx/+; Wnt1- Cret showed perinatal lethality and recapitulated both encephalocele and cleft defects." (PMID 39372737, 2024). "We observed three major gross morphological phenotypes in Gpr161 cKO (Gpr161 f/f; Wnt1-Cre) fetuses; protrusive tectum defect, encephalocele, and craniofacial skeletal defect." (PMID 34887903, 2021). "The Wnt1-Cre lineage-specific deletion of Gpr161 in mice resulted in two significant phenotypes; one involves protrusive tectal defects, while the other are craniofacial skeletal defects, both of which may underlie the development of encephalocele in some fetuses." (PMID 34887903, 2021).
Hypertension (2 papers, 2017 to 2024). The presence of chronic increased pressure in the systemic arterial system. "The aim of this study was to immunohistochemically evaluate and compare the expression of the Fzd8, WNT1, GSK-3β, and β-catenin genes in the hearts of rats with spontaneous hypertension (SHRs) and deoxycorticosterone acetate (DOCA)-salt-induced hypertension." (PMID 38928134, 2024).
microcephaly (2 papers, 2017 to 2023). A congenital or acquired developmental disorder in which the circumference of the head is smaller than normal for the person's age and sex. "In order to further explore the role of Ttc21b in anterior embryonic development and potentially determine the mechanism leading to the microcephaly in Ttc21baln/aln mutants, we used the Wnt1-Cre and Ap2-Cre alleles to ablate Ttc21b in NCC’s and both NCC’s and surface ectoderm, respectively." (PMID 28291836, 2017). "Except for cleft palate, the Wnt1-Cre; Fam20bf/f mice also exhibited microcephaly, widened fontanels, micrognathia, tongue elevation, temporomandibular joint abnormalities, and reduced mineralization in the skull, maxilla, mandible, and palatine." (PMID 37298583, 2023).
Microglossia (2 papers, 2021 to 2023). Decreased length and width of the tongue. "Thus, disrupted myogenesis might be another cause of microglossia observed in Wnt1‐Cre/Nf2cKO mutants at E15.5–E18.5." (PMID 34697858, 2021). "Our previous research has shown that Wnt1-Cre-mediated constitutive activation of Alk2 leads to microglossia, whereas the conditional knockout of Nf2 results in macroglossia during the early stages of embryonic development." (PMID 37680190, 2023).
osteoarthritis (2 papers, 2021 to 2024). A noninflammatory degenerative joint disease occurring chiefly in older persons, characterized by degeneration of the articular cartilage, hypertrophy of bone at the margins and changes in the synovial membrane. "Wnt family member 1 (WNT1) and Wnt family member 10B (WNT10B) are integral components of the Wnt signaling pathway, which plays a critical role in the pathogenesis of osteoarthritis." (PMID 38392197, 2024). "Wnt family member 1 (WNT1) and wnt family member 10B (WNT10B) are involved in the Wnt signaling pathway, which has an established role in osteoarthritis pathogenesis." (PMID 34450027, 2021).
osteopetrosis (2 papers, 2024 to 2025). Osteopetrosis, also known as marble bone disease, is a descriptive term that refers to a group of rare, heritable disorders of the skeleton characterized by increased bone density on radiographs. "Inducing Wnt1 early on affects craniofacial bone without disturbing tooth development, but prolonged embryonic induction leads to postnatal mortality with osteopetrosis-like bone overgrowth and malformed teeth." (PMID 40454459, 2025).
papillary carcinoma (2 papers, 2004 to 2020). A malignant epithelial neoplasm characterized by a papillary growth pattern. "WNT1 has been shown to promote cancer progression because it triggers cell proliferation and metastasis, microRNA-329 inhibits papillary thyroid cancer progression via direct targeting WNT1." (PMID 33113852, 2020).
prostate tumor (2 papers, 2008 to 2020). "Recent studies reported that certain Wnt ligands such as Wnt1 are expressed in prostate cancer cell lines and appear to be elevated in some human prostate tumor tissues." (PMID 18478098, 2008). "Several Wnt ligand including Wnt1 and Wnt2 are up-regulated in human prostate tumor samples." (PMID 18478098, 2008).
psoriasis (2 papers, 2012 to 2020). An autoimmune condition characterized by red, well-delineated plaques with silvery scales that are usually on the extensor surfaces and scalp. "While downregulation of SFRP3 also occurs in psoriasis, SFRP3 is unable to bind to Wnt1 directly, thus placing it outwith the canonical Wnt signalling pathway." (PMID 22384081, 2012).
retinal degeneration (2 papers, 2021 to 2023). Degeneration of the retina. "To test whether the Wg/Wnt1 pathway is relevant to age-dependent disease progression, we examined retinal degeneration in a Drosophila model of ADRP, in which a mutant allele of the Rh-1 gene, ninaEG69D, causes age-dependent retinal degeneration." (PMID 37464094, 2023). "Our study demonstrates that the knockdown of Wg/Wnt1 delays the course of the retinal degeneration phenotype in the Drosophila model of ADRP." (PMID 37464094, 2023). "Altogether, these results indicate that the Wg/Wnt1 signaling pathway mediates the apoptosis of retinal cells under ER stress conditions and plays an essential role in the progression of retinal degeneration in the presence of ER stress." (PMID 37464094, 2023). "However, the knockdown of Wg/Wnt1 in photoreceptor cells using the Rh-1 driver significantly delayed the time course of retinal degeneration, with 66% of the examined flies exhibiting intact Rh-1 > GFP patterns at 28 d (red line)." (PMID 37464094, 2023).
rhabdomyosarcoma (2 papers, 2013 to 2021). A rare aggressive malignant mesenchymal neoplasm arising from skeletal muscle. "Exogenous Wnt1 activates Myf5 expression, resulting in MuSC activation and/or proliferation, as shown in rhabdomyosarcomas." (PMID 34087215, 2021).
Salmonella Infections (2 papers, 2021 to 2022). Infections with bacteria of the genus SALMONELLA. "Based on the previous studies on Wnt protein, we hypothesize that the upregulation of LINC00152 is the host reaction to defense against Salmonella infection and inhibit enteric bacterial-induced inflammation, similar to the role of upregulation of wnt2 and wnt1 in response to Salmonella infection." (PMID 35959377, 2022).
scoliosis (2 papers, 2018 to 2023). A congenital or acquired spinal deformity characterized by lateral curvature of the spine. "We found that patients with COL1A1 and COL1A2 genotypes were strongly biased towards having mild or no scoliosis at all, whereas patients with pathogenic variants on IFITM5, WNT1 and other recessive genes did not display such a pattern." (PMID 37730650, 2023). "Patients with either COL1A1 and COL1A2 were strongly biased toward having mild or no scoliosis, whereas patients with mutations in IFITM5, WNT1 and other recessive genes were more evenly distributed among the four outcome grades." (PMID 37730650, 2023).
systemic sclerosis (2 papers, 2023 to 2024). A chronic disorder, possibly autoimmune, marked by excessive production of collagen which results in hardening and thickening of body tissues. "We and others have demonstrated that canonical WNT ligands, such as WNT1 and WNT10B, are overexpressed in patients with Systemic Sclerosis (SSc) and in other fibrotic diseases." (PMID 38747285, 2024). "In systemic sclerosis patients show high levels of different isoforms of soluble CD146 (scCD146), which are responsible for profibrotic effects through dysregulation of the Wnt-1/ β-catenin pathway and proangiogenic activity via up-regulation of the PKCε pathway." (PMID 36721239, 2023).
Truncus arteriosus (2 papers, 2013 to 2023). A single arterial trunk arises from the cardiac mass. "Conditional mutation N-cadherin and TGF-β receptor Alk2 in neural crest cells by WNT1 Cre leads to persistent truncus arteriosus (PTA) as the CNC cells fail to enter the OFT cushions." (PMID 36745292, 2023). "In addition to the formation of ectopic OFT sympathetic-like neurons, Twist1;Wnt1-Cre CKOs also display completely penetrant persistent truncus arteriosus (PTA)." (PMID 23555309, 2013).
Acetabular dysplasia (1 paper, 2025). A smaller than normal acetabulum that has insufficient femoral head coverage leading to abnormal hip joint contact pressures, instability and pain. "For example, subcutaneous injection of 0.1 mL pcDNA3.1-WNT1 or si-WNT1 cell suspensions in mice produces acetabular dysplasia at the injection site after 5 weeks." (PMID 40591661, 2025).
acute myeloid leukemia (1 paper, 2025). Acute myeloid leukemia (AML) is a group of neoplasms arising from precursor cells committed to the myeloid cell-line differentiation. "WNT1 and WNT2b are expressed at high levels in acute myeloid leukemia (AML) blasts." (PMID 40805157, 2025).